IGF1 (insulin like growth factor 1)
Diseases named in the same sentence as IGF1 in open-access papers (continued):
Sharing a sentence is not in itself a finding about the gene and the disease.
diabetes (continued). "Moreover, among the subjects without diabetes, fasting glucose levels were significantly higher in the low IGF-1 group." (PMID 36418379, 2022). "Whether IGF-1 is activated in PTC patients without diabetes and the specific mechanism and pathway of activation also need more research and demonstration." (PMID 35711846, 2022). "As will be explained later, low levels of IGF-1 at early ages are related to the development of non-communicable diseases such as diabetes, an effect that could be promoted in parallel by high concentrations of the diabetogenic hormone GH in SAM children." (PMID 39816412, 2022). "Serum IGF-1 levels were not related to the prevalence of diabetes (p = 0.64)." (PMID 33746806, 2021). "This study was conducted to compare the levels of IGF-1 and sclerostin in premenopausal women with and without diabetes, as they might be useful as markers of decreased bone formation in premenopausal women with type 2 diabetes." (PMID 34690653, 2021). "IGF-1 serum levels have not usually been found to be increased in diabetes patients." (PMID 33905470, 2020). "This is consistent with an early observation of localized diabetes within the brain, which noted that, in the absence of systemic symptoms of diabetes, insulin and IGF-1 resistance were detectable in the hippocampus and, to a lesser extent, the cerebellar cortex." (PMID 32226608, 2020). "The application of IGF-1 could be considered when an extreme IR or insulin insensitivity exists, while recombinant human IGF-1 might be an alternative strategy to normalize the blood glucose level and prevent acute complications of diabetes." (PMID 33905470, 2020). "In our study, median IGF-1 concentration of 154 μg/L was practically the same as the median value in a larger previous study, where baseline concentrations of IGF-1 below the median of 152 μg/L predicted future risks of impaired glucose tolerance and type 2 diabetes mellitus." (PMID 31191190, 2019). "In addition, epidemiological studies have found a positive association between the risk of developing type 2 diabetes mellitus and circulating IGFBP3 concentrations, with some evidence that these effects are independent of IGF1." (PMID 29947889, 2018). "However, its specific role in the pathogenesis of PSD still needs more discussion, so a certain correlation between diabetes and PSD may be related to the influence on the serum IGF-1 level." (PMID 30181997, 2018). "Furthermore, IL-15 and IGF-1 in the epidermis were regulated by rapamycin and STZ under similar kinetics, which provides additional support for the coordinated suppression of IGF-1 and IL-15 in diabetes." (PMID 28729536, 2017). "However, this is in contrast with published results in which no variations of IGF-1 mRNA is reported in rats after STZ diabetes induction." (PMID 27136480, 2016). "Since Grb10 has been demonstrated to negatively regulate IGF-1/IGF-1R signaling, we then determined whether catalpol-mediated down-regulation of Grb10 expression was coupled to up-regulation of IGF-1/IGF-1R signaling in diabetic kidneys." (PMID 26986757, 2016). "However, additional confounding factors (e.g., age, BMI, and possibly diabetes, infection, dementia and others) may affect IGF-1 and contribute to the generally large variance of IGF-1 within PD patients as well as healthy controls." (PMID 26967642, 2016). "Decreased IGF-1 levels were also observed in adults and older patients affected by diabetes-related CKD (DM-CKD)." (PMID 26779261, 2015). "Systemic illnesses, including catabolic states, hepatic or renal failure, malnutrition, and diabetes mellitus, may decrease the IGF-1 level and result in false-negative values in screening for acromegaly." (PMID 26514337, 2015). "Initial IGF-1 was significantly higher in diabetics (389.38 vs. 285.27, p = 0.001) and specifically in older diabetic men (420.19 vs. 329.44, p = 0.017) compared with those without diabetes." (PMID 25996963, 2015).
diabetes (continued). "It is not clear whether plasma levels of IGF-2 change in diabetes, but like IGF-1, the level of IGF-2 in wound fluid is decreased." (PMID 23671876, 2013). "A lack of IGF-1 expression within the basal layer and fibroblasts may contribute to retarded wound healing in diabetes mellitus patients." (PMID 23671876, 2013). "Although circulating IGF1 levels are known to decline following the onset of type 1 diabetes, our findings suggest that local activation of the IGF pathway within the ovary may represent an adaptive response to counteract diabetes-induced cellular stress or dysfunction." (PMID 41397560, 2026). "Furthermore, the activation of the AKT and mTOR signaling proteins, as well as increased IGF-1 expression, was significantly elevated in the D-T+HIIT group compared to the diabetic control group and other treatment groups, and approached levels observed in the non-diabetes group." (PMID 40362714, 2025). "Notably, however, we obtained data indicating that the prevalence of those with low IGF-1 levels was similar (27.8%) in the subjects without diabetes, suggesting that the prevalence of those with low IGF-1 levels in the present study reflects obese subjects overall." (PMID 36418379, 2022). "Further research is needed to understand the influence of diabetes on native PDL-MSCs on the molecular level and whether using growth factors such as IGFs or their binding proteins would enhance periodontal regeneration in diabetics, in particular IGF-1, IGF-2 and IGFBP-5." (PMID 34940355, 2021). "GH/IGF1 excess did not exert a protective effect on periodontal status in acromegaly, possibly due to concurrent hypogonadism and opposing cytokines; however, it could mask the ill-effects of diabetes on periodontal health." (PMID 33154456, 2020). "Regarding deleterious effects, elderly onset patients with diabetes have lower prevalence of proliferative DR (PDR) than those younger onset patients for similar diabetes duration, which may be related with lower serum IGF-1 levels detected in the older patients." (PMID 30026694, 2018). "Fifteen of the 42 patients had normal IGF-1 (confirmed in two measurements); none of the patients had kidney or liver failure, malnutrition, uncontrolled hypothyroidism or used oral estrogen; six patients had diabetes mellitus, but were compensated at the time of IGF-1 measurement." (PMID 27982199, 2016). "Insulin and insulin-like growth factor-1 (IGF-1) signaling, by IGF-1R, are differentially involved in keratinocyte differentiation, promoting the inhibition of normal keratinocyte differentiation, suggesting that abnormal insulin signaling, as what occurs in diabetes, may lead to skin pathology." (PMID 27840833, 2016). "Taken together, these findings indicate that IGFBP-2 might be a new target of metformin action in diabetes and the metformin-AMPK-Sirt1-PPARα-IGFBP-2 network may provide a novel pathway that could be applied to ameliorate metabolic syndromes by controlling IGF-1 bioavailability." (PMID 27009398, 2016). "In addition, exposure to high levels of GH and IGF-1 for an extended period of time can lead to multiple comorbidities, such as diabetes mellitus (DM) and hypertension, which have a negative impact on kidney function." (PMID 39329880, 2024). "The adjustment for potential confounders such as age, sex, diabetes treatment, BMI, FPG, HbA1c, estradiol, testosterone, 25-hydroxyvitamin D, P1NP, and β-CTX revealed a nonlinear connection between IGF-1 SDS and BMD at LS, FN, and TH." (PMID 39398331, 2024). "Previous studies have stated the negative effect of diabetes and TDF on IGF-1 levels in blood and brain samples." (PMID 35122679, 2022). "Diabetes reduced retinal IGF-2, but not IGF-1 or IR, mRNA levels, and reduced IGF-2 and IGF-1 content in vitreous fluid." (PMID 33915127, 2021). "Kim and colleagues found significantly lower serum IGF-1 levels and Hb concentrations in a group of DM-CKD subjects than in matched CKD patients without diabetes." (PMID 26779261, 2015).
diabetes (continued). "Univariate Logistic Regression analysis revealed that factors such as disease duration, IGF-1, GH, ACTH, cortisol, remission status, surgery, somatostatin use, diabetes mellitus (DM), hypothyroidism, and adrenal insufficiency were not identified as effective risk factors for macroglossia." (PMID 41353330, 2025). "This is unexpected due to the assumption that maternal circulating IGF-1 seems to be the primary source of HM IGF-1, and higher concentrations of serum IGF-1 have been reported in pregnant diabetic women compared with those without diabetes." (PMID 36079876, 2022). "Monocytes also produce growth factors, such as VEGF (vascular endothelial growth factor), IGF-1 (insulin-like growth factor-1), and TGF-β (transforming growth factor-β) in both diabetes and nondiabetes conditions, which are the essential contributors in wound healing." (PMID 35186344, 2022). "Also, in a mice model of T2D with peripheral neuropathy, lower serum levels of IGF-1 and red cell IGF-1 receptor were detected than in non-neuropathic mice with diabetes and non-diabetes controls." (PMID 33905470, 2020). "Thus, IGF-1, mTOR and IL-15 all are suggested to regulate homeostasis of DETCs, but the coordinate regulation of these pathways of DETC homeostasis in diabetes is not well characterized." (PMID 28729536, 2017). "In conclusion, the lack of IGF-1 and the elevated levels of IGF-2 within the basal layer of the epidermis of diabetic patients may be important in delayed wound healing in diabetes mellitus, particularly for chronic foot ulcers." (PMID 23671876, 2013).
acromegaly (753 papers, 2006 to 2026). Acromegaly is an acquired disorder related to excessive production of growth hormone (GH) and characterized by progressive somatic disfigurement (mainly involving the face and extremities) and systemic manifestations. "Acromegaly is an endocrine disorder resulting from a dysregulated hypersecretion of growth hormone and its target hormone, insulin-like growth factor 1 (IGF-1), usually caused by a growth hormone-secreting pituitary adenoma." (PMID 41497147, 2026). "Exploratory studies conducted in patients with acromegaly demonstrated the potential role of total ER and a ketogenic diet in reducing IGF-1 levels; however, these approaches are associated with safety and adherence concerns." (PMID 41472889, 2026). "This case report describes a rare presentation of paraneoplastic acromegaly caused by IGF-1 excess secondary to hepatic malignancy in an elderly patient." (PMID 41497147, 2026). "This study reveals how excess GH and IGF‐1 alter brain activity, offering new insights into the neurobiological mechanisms underlying cognitive decline in acromegaly." (PMID 41550023, 2026). "Acromegaly is a chronic multisystem disorder in which growth hormone and insulin-like growth factor 1 excess cause progressive somatic, metabolic, psychological, and functional morbidity." (PMID 42014048, 2026). "Acromegaly is an endocrine disorder characterized by excessive growth hormone (GH) and insulin-like growth factor-1 (IGF-1) levels, commonly caused by a pituitary adenoma." (PMID 40167828, 2025). "Both in humans and cats, increased serum IGF-1 is associated with acromegaly, a condition where excess IGF-1 is produced in response to pituitary derived excess synthesis of growth hormone." (PMID 40001060, 2025). "Excess GH and IGF-1 in acromegaly cause endothelial dysfunction through various mechanisms, such as increased levels of oxidative stress and reduced anti-oxidant capacity, evidenced by decreased nitric oxide (NO)." (PMID 40142714, 2025). "As further evidence of its action to lower IGF-1, clomiphene has been shown to normalize IGF-1 levels in 7/16 (44%) patients with acromegaly and was associated with a concomitant 209% increase in total testosterone (TT) levels." (PMID 40421427, 2025). "Background/Objectives: Acromegaly is a rare chronic disease caused by excess growth hormone (GH) and insulin-like growth hormone 1 (IGF-1) due to a pituitary adenoma." (PMID 40559129, 2025). "The cause of acromegaly is an overproduction of GH and high IGF-1 levels, in most patients secondary to a pituitary gland adenoma." (PMID 41567317, 2025). "Here, we present the case report of a male patient in his 50 s with a secreting mixed somatolactrotroph macrotumor causing acromegaly and elevated IGF-1 levels." (PMID 40523964, 2025). "Acromegaly is a rare disease characterized by excess secretion of growth hormone (GH) and insulin-like growth factor 1 (IGF-1), which in approximately 99% of cases is caused by a benign GH-secreting pituitary adenoma." (PMID 40429391, 2025). "Acromegaly is caused by an excessive secretion of growth hormone and the secondary elevation of IGF-1 levels, leading to progressive changes in multiple body systems, including the craniofacial region and oral cavity." (PMID 40807135, 2025). "Acromegaly is a rare disease caused by increased growth hormone secretion due to a pituitary adenoma, resulting in increased levels of circulating insulin-like growth factor 1 (IGF-I)." (PMID 39944202, 2025). "Acromegaly management includes surgery, medical therapy, and RT and aims to reduce the GH and IGF-1 levels, manage tumor volume, decrease the risk of creating systemic concomitant disease, and decrease mortality." (PMID 41334063, 2025). "Multiple studies have identified various GH and IGF-1 target sites within ocular tissues, supporting an association between acromegaly and a spectrum of ocular abnormalities." (PMID 41220589, 2025).
acromegaly (continued). "Acromegaly, characterized by excess GH and subsequent IGF-1 elevation, is known to increase the risk of several neoplasms." (PMID 41479497, 2025). "Acromegaly is caused by dysregulated hypersecretion of growth hormone (GH), leading to an overproduction of insulin-like growth factor 1 (IGF-1)." (PMID 41303810, 2025). "An association between colorectal cancer and acromegaly has been investigated, and IGF-1 and GH excess are clearly implicated in the mechanisms of colon carcinogenesis." (PMID 40088375, 2025). "Acromegaly is typically caused by a GH‐secreting pituitary adenoma that drives excess secretion of IGF‐1." (PMID 40079729, 2025). "Acromegaly is a chronic and rare endocrine disorder, predominantly caused by GH-secreting pituitary adenomas, leading to persistently elevated IGF-1." (PMID 41458762, 2025). "The risk factors for developing cardiac abnormalities in acromegaly are prolonged hypersecretion of GH/IGF-1, diagnostic delay, higher body mass index (BMI), and increasing age." (PMID 40429391, 2025). "A prospective study in 2024, conducted in a large cohort of patients with acromegaly reported that cancer risk correlated with both the degree and duration of excess IGF-1." (PMID 40088375, 2025). "Cardiovascular disease (CVD) is a frequent comorbidity in acromegaly, driven by GH/IGF-1 hypersecretion, disease duration, and conventional risk factors." (PMID 40842744, 2025). "Patients with a baseline IGF-1 value below 500 μg/L had a lower risk of having an uncontrolled acromegaly over time, while those with IGF-1 ≥700 μg/L showed a higher risk." (PMID 38197875, 2024). "Acromegaly is a rare hormonal disorder caused by excessive secretion of growth hormone (GH) and insulin-like growth factor-1 (IGF-1), which usually occurs in benign pituitary tumors.." (PMID 39220366, 2024). "Excessive secretion of GH and IGF-1 in acromegaly causes increased bone turnover, which is reflected in higher concentrations of bone formation and bone resorption markers." (PMID 39741885, 2024). "Acromegaly is a rare disease caused by excessive secretion of growth hormone (GH) and its peripheral mediator, insulin-like growth factor-1 (IGF-1)." (PMID 39741885, 2024). "Despite precocious puberty occurring in most MAS patients, the final height is usually normal in adults with MAS and acromegaly, probably due to the association of GH/IGF-1 excess with elevated sex hormones." (PMID 39194755, 2024). "This is a rare and paradoxical case of pituitary tumor causing acromegaly-associated symptoms despite normal GH and IGF-1 levels." (PMID 39044175, 2024). "Earlier research has also linked taurine and glyceric acid to IGF-1 levels, suggesting their potential as metabolomic biomarkers for active acromegaly." (PMID 39669498, 2024). "According to the studies covered in this article, acromegaly is significantly associated with hyperglycemia and GH, IGF-1 being the primary mediators for the pathophysiology behind deranged glucose parameters in acromegalic patients." (PMID 39119396, 2024). "Univariate analysis showed that age <40 years, normal or overweight, baseline IGF-1 <300 μg/L or ranged between 300 and 500 μg/L, and all pegvisomant dose <20 mg/day were associated with a lower probability of acromegaly uncontrol." (PMID 38197875, 2024). "The results of regression analysis support a direct impact of IGF1 levels on cardiac structure in patients with acromegaly, underlining the importance of disease control in these patients." (PMID 38847918, 2024). "Therapeutic modalities for acromegaly aim to normalize serum GH and IGF-1 levels, reduce mortality risk, improve clinical symptoms, and control tumor size through surgical or medical interventions." (PMID 39399792, 2024). "The manifestations of acromegaly are caused by an increased GH secretion by pituitary tumor and, as a consequence, increased IGF-1 levels." (PMID 38668933, 2024).